RNY3P16 (RNY3 pseudogene 16)
Gene: Miscellaneous RNA gene on chromosome X (119,456,558 to 119,456,658, forward strand). Ensembl gene ENSG00000252147.
Homologues: Orthologues: chimpanzee Y_RNA (99% identical), macaque Y_RNA (95% identical). Paralogues in human: Y_RNA (91% identical), RNY3 (90% identical), Y_RNA (90% identical), Y_RNA (89% identical), RNY3P1 (88% identical), Y_RNA (88% identical), Y_RNA (87% identical), RNY3P14 (86% identical), Y_RNA (86% identical), RNY3P11 (85% identical), Y_RNA (85% identical), RNY3P4 (84% identical), and 96 more.